STAT3 (signal transducer and activator of transcription 3)
Diseases named in the same sentence as STAT3 in open-access papers (continued):
Sharing a sentence is not in itself a finding about the gene and the disease.
glioma (continued). "However, the action of the JAK2/STAT3 signaling pathway in glioma cell EMT and glioma stem cells has not been fully elucidated." (PMID 33788424, 2021). "The CRNDE promotes malignant progression of glioma by acting as a ceRNA sponge for miR-384 and inhibiting the activation of miR-384 target piwi-like RNA-mediated gene silencing 4 (PIWIL4) and its downstream protein signal transducer and activator of transcription 3 (STAT3)." (PMID 33800703, 2021). "Tyrosine-specific phosphoproteomic analysis of IL-33+ tumors showed an increase in a number of phospho-peptides derived from STAT3, CDK1, CDK2, FYN, MAPK14, and MAPK3, some that based on amino acid sequence could be attributed to either human glioma or mouse host origin." (PMID 33020472, 2020). "STAT3 mRNA expression in WHO grade III gliomas (including anaplastic astrocytoma (AA), anaplastic oligodendroastrocytoma (AOA) and anaplastic oligodendroglioma (AO)) was higher than that in WHO grade II gliomas (including astrocytoma (A), oligodendroastrocytoma (OA), and oligodendroglioma (O))." (PMID 32483429, 2020). "In a therapeutic setting, intracranial application of the siRNA-containing LPP leads to knockdown of STAT3 target gene expression, decreased tumor growth and significantly prolonged survival in Tu2449 glioma-bearing mice compared to negative control-treated animals." (PMID 30857197, 2019). "Activation of ALK/STAT3 in T cell lymphoma, AP-1/JAK/STAT in classical Hodgkin lymphoma (cHL), the microRNA-200/ZEB1 axis in non-small-cell lung cancer (NSCLC), c-jun/STAT3 in BRAF inhibitor-resistant melanoma, and PI3K in glioma have each been reported to upregulate PD-L1 expression on tumor cells." (PMID 31730010, 2019). "Six canonical pathways; Axonal guidance signaling, FGF signaling, Glioma Signaling, STAT3 signaling, ERK/MAPK and AMPK signaling, which are highly important in astrocytic functions, were predicted to be dysregulated by ZIKV infection by 48 hpi, with Z-scores exceeding ± 1.96." (PMID 30984137, 2019). "However, less report has dealt with the direct correlation of STAT3 and FOXP1 in glioma cells." (PMID 30134017, 2018). "Interestingly, miR-124 inhibited the migration and invasion of glioma cells through down-regulation of ROCK1, SOS1, CDK4, STAT3, and PPP1R13L expression, indicating miR-124 may be a valuable biomarker for glioma." (PMID 28060761, 2017). "Collectively, miR-6743-5p may act as an oncomiRNA in glioma by targetting GRIM-19 and STAT3." (PMID 29074558, 2017). "Activation of STAT3 involves a series of events, and recent research identified that STAT3 downstream genes are overexpressed in the mesenchymal GBM subtype, supporting that STAT3 signaling has a key function in controlling mesenchymal transformation in glioma." (PMID 28415635, 2017). "Therefore, we speculate that STAT3/MMP2 signalling may be involved in SH3GL2 mediated migration and invasion of glioma cells." (PMID 28470949, 2017). "Moreover, downregulation of STAT3 signaling using a specific inhibitor or a neutralizing gp130 antibody failed to confer radiosensitivity to glioma cells." (PMID 29246031, 2017). "In addition, AKT and STAT3 has been confirmed to be involved in the regulation of downstream factors including PCNA, Bcl2, CyclinD1 and VEGF, which are related to tumor proliferation, apoptosis and angiogenesis in glioma cells." (PMID 27893430, 2016). "Taking together, we for the first time found that IL-10 from M2 macrophage promoted proliferation of glioma through interaction with JAK2; thereby activating the JAK2/STAT3 pathway, indicative of IL-10 could be used as a therapeutic target in the curing of glioma." (PMID 27765933, 2016). "Signal transducer and activator of transcription 3 (STAT3) is reported to have a diversity of biological functions in regulating cell proliferation, differentiation, apoptosis, inflammation, oncogenesis and angiogenesis in many kinds of tumors including glioma." (PMID 26378521, 2015).
glioma (continued). "Functional studies, using U251MG glioma cells and primary tumor cell lines derived from glioma patients expressing different levels of CB1, highlighted SR141716 efficacy in inducing apoptosis via G1 phase stasis and block of TGF-β1 secretion through a mechanism that involves STAT3 inhibition." (PMID 26008966, 2015). "In summary, these results strongly suggest that RTVP-1 mediates the mesenchymal transformation of glioma cells, at least partly, via the IL-6 pathway and points to the existence of positive regulatory pathways linking RTVP-1 and IL-6 via the activation of the STAT3 pathway." (PMID 26267319, 2015). "Using gene array analysis of RTVP-1 silenced glioma cells we identified IL-6 as a mediator of RTVP-1 effects on the mesenchymal transformation and migration of GSCs, therefore acting in a positive feedback loop by upregulating RTVP-1 expression via the STAT3 pathway." (PMID 26267319, 2015). "In glioma cells, the up-regulation of MMP-13 by leptin was mediated through p38 MAP kinase and NF-κB pathway, while in pancreatic cancer cells, we found that the expression of MMP-13 was regulated through JAK2/STAT3 signaling pathway in response to leptin stimulation." (PMID 25948792, 2015). "DCA decreased the expression of Taldo, Stat3, Sox2 and Gata6 in glioma spheroids but not in NSCs." (PMID 24481450, 2014). "Interestingly, there is no published information related to how STAT3 activation would alter wild type (WT) HSV1 or oHSV replication in gliomas." (PMID 23936533, 2013). "This would be consistent with the previously documented role of glioma-infiltrating myeloid cells such as macrophages and microglia playing a central role in the angiogenic and invasive mechanisms of resistance by the STAT3 pathway and having a negative prognostic influence on survival." (PMID 23013619, 2012). "This suggests that Src and STAT3 may be an ideal target for glioma therapy since inhibition of STAT3 signaling induces tumor cell death, but does not kill normal astrocytes." (PMID 20808823, 2010). "Moreover, in patients with glioma that were without progression, p-STAT-3 levels were within the healthy donor range." (PMID 19900287, 2009). "Furthermore, the percent of PBMCs displaying p-STAT-3 in glioma patients was not directly correlated with the fraction of Tregs in the CD4 compartment." (PMID 19900287, 2009). "Also, in another study, it was discovered that nano-DOX impedes STAT3 activation in tumor cells and lowers IL-6 production in astrocytes, indicating that nano-DOX has the potential to break the STAT3/IL-6-mediated reciprocal activation loop among glioma cells and astrocytes." (PMID 38686045, 2024). "Although various IFNG-related inflammatory responses may be active in the glioma microenvironment with elevated IFNGR scores, macrophages with increased expression of IFNGR1 and IFNGR2 were preferentially subject to transcriptional regulation by NF-κB and STAT3." (PMID 35492352, 2022). "Therefore, glioma cells lacking miR-21 might upregulate the Stat3 pathways involved in tumor progression." (PMID 35572197, 2022). "Therefore, a comprehensive understanding of the abnormal expression of members of the JAK2/STAT3 signaling pathway and the effects on the classic EMT process and cancer stem cells provide new ideas for the development of methods to effectively inhibit the malignant progression of glioma." (PMID 33788424, 2021). "Additionally, MDK, which is upregulated by Wnt/β-catenin in gliomas, contributes to tumor progression and metastasis by enhancing the growth, survival, and EMT of cancer cells; this is because MDK activates a Notch signaling that cross-talks with PI3K/AKT and STAT3 signaling." (PMID 32120790, 2020). "Remarkably, and supporting the important role of the tumor microenvironment, nontumorigenic glioma-associated mesenchymal stem cells (MSCs) are able to increase the proliferation and self-renewal of GSCs by secreting IL6 in a paracrine fashion by inducing the STAT3 pathway in GSCs." (PMID 32722427, 2020).
glioma (continued). "Moreover, gliomas induce GAMs to substantially decrease the expression of MHC molecules and pro-inflammatory cytokines (TNF-α) while increasing the secretion of transcription factor, STAT3, likely through S100B-receptor for advanced glycation end produces (RAGE) axis." (PMID 26217588, 2015). "We show that conditioned media from the selection of adult but not pediatric Glioma-Inducing Cells (GICs) maintain mESCs’ pluripotency in correlation with LIF secretion and activation of STAT3 protein." (PMID 38137514, 2023). "Overall, the mRNA levels of ACVR1, STAT3, WNT5A, KLF4 and DMC1 were obviously decreased in glioma samples with 1p19q codeletion compared to those in glioma samples without 1p19q codeletion." (PMID 36435765, 2022). "In the PPI network of CLCF1, the signal transducer and activator of transcription 3 (STAT3) is upregulated in PTEN-mut but not in the PTEN-wt subgroup (PTEN-mut vs. Normal, PTEN-wt vs. Normal), showing STAT3 is correlated with PTEN-mut glioma." (PMID 34336645, 2021). "The expression of p-STAT3 was hardly detected in nontumor brain tissue and WHO grade II glioma tissue, while it was abundant in WHO grade III glioma tissue and GBM tissue." (PMID 32483429, 2020). "Western blot analyses demonstrated that, whereas STAT2 and STAT4 showed no prominent or consistent changes in expression, STAT1, STAT3 and STAT5 expression were increased in glioma tissues compared with neighboring non-tumor tissue." (PMID 31530290, 2019). "Notably, other than RPN2, which has been shown to promote radioresistance via upregulating STAT3 signaling in gliomas, none of the genes in ESURATAG-GS have been studied in the context of glioma, highlighting the novelty of our findings." (PMID 40718795, 2025). "Although the combination with a STAT3 inhibitor did not further enhance STING agonist activity, the addition of anti-PD-1 antibodies to 8803 treatment enhanced survival in an immune checkpoint blockade-responsive glioma model." (PMID 38941297, 2024). "As addressed in the present review, elements of TEM also contribute to TMZ resistance, such as immunosuppressive TAMs due to activation of the STAT3-MYC signaling pathway and the presence of gap junctional communication between glioma cells and non-neoplastic astrocytes." (PMID 38275375, 2023). "The results showed that 2.0 mM VPA or 5 mg/ml Coptis Chinensis could reduce the expression of P-STAT3, and Coptis Chinensis down-regulated HDAC3 and P-STAT3 in glioma cells, but it did not reduce the expression of STAT3." (PMID 29212474, 2017). "Importantly, preliminary analysis confirms that STAT3 is not among our candidate genes, suggesting that multiple pathways contribute to TAM dysfunction in gliomas." (PMID 23737783, 2013). "Thus, to further analyze the regulation carried out by STAT3, we evaluated the expression of PD-L1 on circulating monocytes and found that the percentage of monocytes expressing PD-L1 was significantly increased on grade III and IV gliomas, but not in grade II." (PMID 35069595, 2021).
colorectal cancer (809 papers, 2010 to 2026). A primary or metastatic malignant neoplasm that affects the colon or rectum. "The JAK2/STAT3 pathway is an important driver of tumor progression, immune evasion, and therapy resistance; persistent STAT3 activation is linked to poor prognosis in multiple malignancies, including esophageal, breast, and colorectal cancer." (PMID 40761486, 2025). "Among genes with defective expression, it is also noteworthy to mention MCC (Mutated In Colorectal Cancers), which is specifically down-regulated in STAT3-mutated cases." (PMID 40721648, 2025). "IL-6 further supports tumor growth through the activation of STAT3, a transcription factor implicated in cancer cell proliferation and metastasis in colorectal cancer cells." (PMID 40143078, 2025). "Our study showed that FK866 can cause ferroptosis in colorectal cancer cells via the Stat3/Gpx4 axis, suggesting a potential therapeutic avenue for targeting the Stat3‐Gpx4 pathway." (PMID 40492508, 2025). "Research have claimed that Alistipes has a pathogenic effect on colorectal cancer through the IL-6/STAT3 pathway and has been linked to depression." (PMID 38774867, 2024). "Studies have reported that STAT3 overexpression plays a crucial pathogenic role in the development, progression and metastasis of colorectal cancer." (PMID 38486162, 2024). "In a study on colorectal cancer, Teppei Morikawa and others analyzed the p-STAT3 immunohistochemical staining results of 724 colorectal cancer pathologies and found that p-STAT3 was significantly associated with poor prognosis in colorectal cancer patients." (PMID 38710698, 2024). "In contrast, other studies indicated that Alistipes are pathogenic in colorectal cancer by activating the IL-6/STAT3 pathway." (PMID 38390939, 2024). "Comprehensive bioinformatics analysis revealed a significant increase in PDIA3 expression in colorectal cancer, associated with STAT3, CD274, and markers of monocytic/macrophage lineage." (PMID 38761176, 2024). "Increased activity of IL-6 and STAT3 is associated with a poor prognosis in several types of cancer, including colorectal cancer." (PMID 39061221, 2024). "Aberrant STAT3 activation is observed in most colorectal cancer patients and is associated with reduced overall survival." (PMID 38600086, 2024). "Activated (p)STAT1 and (p)STAT3 have often been assigned a role as oncogenic factors, including in melanoma whereas in prostate, lung and colorectal carcinomas, tumor suppressive roles were associated with STAT3 function depending on the mutational context." (PMID 38705997, 2024). "In colorectal cancer, sustained activation of STAT3 is linked to increased cellular multiplication and invasion in vitro and tumor growth in vivo, while blocking STAT3 activity can induce apoptosis and reduce cancer cell invasion." (PMID 37970406, 2023). "Studies have shown that they can enhance susceptibility to colorectal cancer and arthritis by interfering with IL-6/STAT3 signaling pathway and bile acid metabolism." (PMID 37908541, 2023). "ZNF460 (zinc finger protein 460) is involved in the regulation of multiple cancer processes by JAK2/STAT3 pathway, and its high expression is associated with the proliferation, invasion, and metastasis of colorectal cancer and oral cancer." (PMID 36639776, 2023). "IL10RA encodes a receptor molecule for the inflammatory factor IL10 and is associated with IL10 expression and STAT3 phosphorylation in colorectal cancer." (PMID 35432443, 2022). "The aim of this study was to determine the role of STAT3 activation in a frequent subset of fibroblasts during the development of inflammation-associated colorectal cancer in vivo." (PMID 35326623, 2022). "Activation of STAT3 is frequently detected in primary human colorectal carcinoma cells, as well as established human colorectal cancer cell lines, and is commonly associated with a worse prognosis." (PMID 35056682, 2022).
colorectal cancer (continued). "Berberine-induced inhibition of the TLR4/NF-κB/IL-6/STAT3 pathway reduced malignant transformation and cancer recurrence in colitis-associated colorectal carcinoma models." (PMID 36700235, 2022). "piR-54265 accelerates colorectal cancer proliferation and causes therapy resistance to anti-tumor agents by influencing STAT3 phosphorylation." (PMID 34249688, 2021). "The interconnection of signaling pathways such as Wnt/β-catenin, Nrf2-ARE, NF-κB and STAT3 and their aberrations lead to disturbance of cell homeostasis and are the main causative factors involved in the development of colorectal cancer cells." (PMID 34443375, 2021). "Signal transducer and activator of transcription 3 (STAT3) is a critical transcription factor that has been firmly associated with colorectal cancer (CRC) initiation and development." (PMID 34440220, 2021). "For instance, transgenic mice with the Cre recombinase expression under the control of the Col1a2 promoter to selectively delete Stat3 have been reported and indicate that CAFs promote colitis-associated colorectal cancer in a STAT3-dependent manner." (PMID 34858425, 2021). "The result indicated that STAT3 was positively associated with HSPA5 in patients with colorectal cancer (r2 = 0.12, p < 0.0001)." (PMID 33023006, 2020). "As reported in previous studies, high concentrations of phosphorylated STAT3 (p-STAT3) was reported to be associated with high metastatic rate of a majority of human cancers such as lung, ovarian, colorectal cancers and TNBC and their poor survival outcomes." (PMID 32922496, 2020). "In colorectal cancer, IL-6/IL-11-dependent STAT3 activation in cancer-associated fibroblasts promoted tumor development and also correlated with poor prognosis." (PMID 32865617, 2020). "The altered activity of STAT3 was linked to chronic inflammation and somatic mutations that contribute to chronic colitis and the development of colorectal cancer." (PMID 32552789, 2020). "In particular, the importance of Jak/Stat3 signalling in intestinal tumorigenesis is well established and associated with the hyperproliferative and invasive phenotype of human colorectal cancer (CRC)." (PMID 32467235, 2020). "It has been observed that rapid colorectal cancer progression in STING-deficient mice is associated with STAT3 hyperactivation." (PMID 32972405, 2020). "STAT3 activity has previously been associated with paclitaxel resistance in ovarian and colorectal cancer cell lines." (PMID 32231398, 2020). "Chronic inflammation is regarded as an important risk factor for the development of colorectal cancer, and IL-6/STAT3 activation seems to take a center stage in human cancer development." (PMID 32422984, 2020). "Previous studies implicated that STAT-3 and NF-κB modulate colorectal cancer progression and metastasis." (PMID 32222879, 2020). "Accumulative evidence suggested that aberrant activation of STAT3 was intimately associated with the incidence of colorectal cancer." (PMID 30905249, 2019). "This toxin induces STAT3 signaling via Th17 responses that results in the production of IL-17 and IL-22, and other cytokines linked to human colorectal cancer by activating the STAT3 pathway." (PMID 31081530, 2019). "In the recent years, there are many researches on the relationship between STAT3 and cancers, and these research suggest that the activation of STAT3 is closely associated with colorectal cancer." (PMID 31299960, 2019).